SPINT4 (serine peptidase inhibitor, Kunitz type 4)
Synonyms: C20orf137; dJ601O1.1
Tractability: Antibody: UniProt places it where antibodies can reach, with high confidence; UniProt predicts a signal peptide or a membrane-spanning region; its Gene Ontology location is reachable by antibodies, with medium confidence.
Gene: Protein-coding gene on chromosome 20 (45,722,347 to 45,725,830, forward strand). Ensembl gene ENSG00000149651.
Subcellular location: Secreted
Gene Ontology:
Molecular function: serine-type endopeptidase inhibitor activity
Cellular component: extracellular region
Genetic constraint (gnomAD): Loss-of-function variants: 6 observed, 8.1 expected, observed/expected ratio (o/e) 0.74, 90% interval 0.4 to 1.45. That is too few expected variants to judge how well the gene tolerates losing a copy. Missense variants: 101 observed, 111.67 expected, observed/expected ratio (o/e) 0.9, 90% interval 0.77 to 1.07. Synonymous variants: 35 observed, 39.87 expected, observed/expected ratio (o/e) 0.88, 90% interval 0.67 to 1.16.
Homologues: Orthologues: chimpanzee SPINT4 (100% identical), macaque SPINT4 (91% identical), dog SPINT4 (72% identical), rabbit SPINT4 (66% identical), guinea pig SPINT4 (65% identical), mouse Spint4 (58% identical), rat Spint4 (58% identical), zebrafish spint1b (27% identical), tropical clawed frog spint1 (25% identical), Caenorhabditis elegans C54D10.10 (24% identical), Caenorhabditis elegans Y43F8B.3 (24% identical), zebrafish spint1a (24% identical), and 12 more. Paralogues in human: SPINT1 (28% identical), TFPI (28% identical), TFPI2 (28% identical), WFIKKN1 (26% identical), AMBP (25% identical), WFIKKN2 (24% identical), WFDC8 (22% identical), EPPIN (21% identical), KIAA0319L (20% identical), KIAA0319 (19% identical), SPINT2 (14% identical), LRP11 (10% identical), and 1 more.
Diseases named in the same sentence as SPINT4 in open-access papers:
SPINT4 is named in the same sentence as 1 disease in open-access papers, as found by Europe PMC text mining. Sharing a sentence is not in itself a finding about the gene and the disease.
SPINT4 shares sentences with these, for which no sentence is quoted: Infertility (1 paper).